IGLJ2 (immunoglobulin lambda joining 2)
Gene: Immunoglobulin joining (J) gene on chromosome 22 (22,899,481 to 22,899,655, forward strand). Ensembl gene ENSG00000211676.
Homologues: Paralogues in human: IGLJ3 (60% identical).